USP18 (ubiquitin specific peptidase 18)
Diseases named in the same sentence as USP18 in open-access papers (continued):
Sharing a sentence is not in itself a finding about the gene and the disease.
lung carcinoma (continued). "The relationship between USP18 expression and lung cancer metastasis was explored using two syngeneic lung cancer models." (PMID 35387560, 2022). "In contrast, gain of 14-3-3ζ expression rescued this ability of lung cancer cells despite engineered USP18 repression." (PMID 35387560, 2022). "Two distinct syngeneic murine lung cancer metastasis models were interrogated after transplantation of lung cancer cells having engineered USP18 repression as compared to controls." (PMID 35387560, 2022). "Migration and invasion assays were performed with lung cancer cells independently transfected with USP18-targeting siRNAs or control siRNAs along with transfection of a 14-3-3ζ expression vector or a control vector." (PMID 35387560, 2022). "In both models, lung metastases after injection into recipient mice of USP18-knocked-down lung cancer cells repressed USP18 expression and metastases versus controls." (PMID 35387560, 2022). "Our findings established that USP18 inhibition reduced lung cancer metastasis by repressing 14-3-3ζ protein expression." (PMID 35387560, 2022). "RPPAs performed after USP18 knock-down highlighted 14-3-3ζ as a key mediator of the lung cancer metastasis process." (PMID 35387560, 2022). "The expression of USP18 has been shown to be deregulated in lung cancer, breast cancer, bladder cancer and melanoma." (PMID 32957626, 2020). "The low expression of USP18 can significantly reduce the metastasis and invasion of lung cancer cells." (PMID 32742193, 2020). "Recently, data collected on lung cancer cell lines established USP18 as a potential regulator of PTEN protein levels and stability." (PMID 31658294, 2019). "When USP18 expression was repressed in the ED1 murine lung cancer cell line, only ~44% of PTEN protein was stabilized after 8 hours of CHX treatment as compared to controls." (PMID 27980214, 2017). "In contrast to USP18 repression studies, when USP18 was overexpressed in HOP62 human lung cancer cell lines, PTEN levels increased by over 70% compared to vector control transfected cells." (PMID 27980214, 2017). "Engineered loss versus gain of USP18 expression respectively decreased and increased PTEN protein levels and stability in murine and human lung cancers." (PMID 27980214, 2017). "In marked contrast, murine and human lung cancer cell lines having repressed USP18 expression profiles significantly (P < 0.001) decreased cytosolic relative to nuclear PTEN protein levels." (PMID 27980214, 2017). "These cases showed a statistically significant (P < 0.0001) correlation between PTEN and USP18 expression in human lung cancers." (PMID 27980214, 2017). "Both ED1 murine and HOP62 human lung cancer cell lines engineered with stable knockdown of USP18 were used to monitor expression of 304 growth-regulatory proteins that contribute to tumorigenesis in an RPPA." (PMID 27980214, 2017). "Reverse-phase protein arrays (RPPAs) of lung cancer cell lines engineered with repressed USP18 expression uncovered PTEN as a potential target of the ISGylation pathway." (PMID 27980214, 2017). "The translational relevance of this work was confirmed in human lung cancer arrays that revealed USP18 and PTEN immunostaining were positively correlated." (PMID 27980214, 2017). "In contrast, engineered gain of USP18 expression in these same lung cancer cell lines stabilized PTEN protein." (PMID 27980214, 2017). "Based on the displayed contingency table, lung cancer cases with high PTEN expression exhibited high USP18 levels." (PMID 27980214, 2017). "Immunoblotting of PTEN levels in murine and human lung cancer cell lines with engineered knockdown versus overexpression of USP18 (as compared to controls) established USP18 as a regulator of PTEN protein levels and stability." (PMID 27980214, 2017).
lung carcinoma (continued). "Using reverse-phase protein arrays (RPPAs), this study reports that engineered loss of the DUB USP18 destabilized the tumor suppressor protein phosphatase and tensin homologue (PTEN) in both murine and human lung cancer cell lines." (PMID 27980214, 2017). "As activity-based protein profiling can determine DUB activities in different pathophysiological conditions, we chose to profile USP18 activity in lung carcinoma cell lines based on the analysis of expression and gene effect observed from the Broad DepMap database." (PMID 39843430, 2025). "Notably, targeted repression of USP18/UBP43, a regulator associated with ISG15, has been demonstrated to reduce proliferation and increase apoptosis in lung cancer and acute promyelocytic leukemia cell lines." (PMID 38400136, 2024). "Intriguingly, USP18 knock-down reduced lung cancer metastasis." (PMID 35387560, 2022). "Engineered reduction of USP18 expression repressed lung cancer growth and promoted apoptosis." (PMID 35387560, 2022). "A direct link was found between USP18 and lung cancer metastasis." (PMID 35387560, 2022). "Since 14-3-3ζ protein expression was regulated by altering USP18 activity, it was hypothesized that USP18 regulated lung cancer migration and invasion by controlling 14-3-3ζ expression." (PMID 35387560, 2022). "USP18 knock-down significantly inhibited the lung cancer metastasis cascade." (PMID 35387560, 2022). "In summary, this study discovered a novel consequence of decreased USP18 activity in lung cancer." (PMID 35387560, 2022). "Reverse Phase Protein Arrays (RPPAs) were performed to find proteins that were regulated by USP18 knock-down and could reduce lung cancer migration, invasion, and metastasis." (PMID 35387560, 2022). "Similarly, it was previously shown that engineered gain of USP18 expression in human lung cancer cell lines stabilized PTEN protein by preventing its ISGylation post-translational modification pathway." (PMID 31658294, 2019). "Together, these data confirmed that USP18 affected PTEN expression in human lung cancers." (PMID 27980214, 2017). "Thus, USP18 knock-down repressed lung cancer cellular invasion." (PMID 35387560, 2022). "USP18 has been shown to stabilize phosphatase and tensin homolog (PTEN) in both murine and human lung cancer cell lines." (PMID 32957626, 2020). "Our prior work found that USP18 affected stability of cyclin D1 and KRAS, proteins that are overexpressed or constitutively activated in lung cancer cases [19 and LM Mustachio personal communication]." (PMID 27980214, 2017). "While PTEN protein levels in the cytosol decreased in lung cancer cell lines with repressed USP18 expression (compared to vector control), PTEN levels in the nucleus remained similar between vector control and USP18 shRNA-expressing lung cancer cell lines." (PMID 27980214, 2017). "Of 507 lung cancer cases evaluated in the lung cancer array, analyses were conducted in 461 cases that were adequately immunostained for both PTEN and USP18 expression profiles." (PMID 27980214, 2017). "Quantification of PTEN protein levels after USP18 repression in ED1 and HOP62 lung cancer cell lines revealed a reduction of PTEN protein by at least 50% as compared to vector control cells." (PMID 27980214, 2017). "In subsequent studies, engineered repression of USP18/UBP43 (ISG15 deconjugating enzyme) was shown to destabilize PML-RARα, reduce proliferation, and increase apoptosis in acute promyelocytic leukemia and lung cancer cell lines." (PMID 35159348, 2022). "Furthermore, USP18 deubiquitinates and stabilizes Kirsten rat sarcoma viral oncogene homolog (KRAS), thereby leading to the promotion in aggressiveness of lung cancer." (PMID 32957626, 2020). "A human lung cancer microarray was immunostained for PTEN and USP18." (PMID 27980214, 2017). "Total PTEN levels decreased with USP18 loss and PTEN levels in the nucleus (between vector control and USP18 shRNA-transfected lung cancer cells) did not appreciably change." (PMID 27980214, 2017).
lung carcinoma (continued). "Given that USP18 and PTEN profiles are significantly (P < 0.0001) associated in human lung cancers, it is not surprising that the ISGylation can affect PTEN expression in malignant tissues." (PMID 27980214, 2017). "PTEN and USP18 expressing lung cancer cases were examined for independent groups based on absent, low, medium, or high PTEN and USP18 immunostaining profiles." (PMID 27980214, 2017).
breast carcinoma (15 papers, 2018 to 2025). "USP18 levels are elevated in diverse cancers and loss of USP18 has been shown to be tumour suppressive in mouse models of human mammary cancer." (PMID 37756534, 2023). "USP18 is negatively associated with cell apoptosis in breast cancer." (PMID 38087046, 2024). "Biologically, KCTD10 and USP18 confer breast cancer cells’ sensitivity or resistance to ferroptosis, respectively, via targeting SLC7A11." (PMID 38959043, 2024). "Significantly, USP18 knockdown sensitized breast cancer cells to ferroptosis, induced by cystine deprivation, treatment with RSL3, or Erastin, which was all rescued by Ferr-1." (PMID 38959043, 2024). "Collectively, KCTD10 has growth-suppressive, while USP18 has growth-promoting role in breast cancer cells." (PMID 38959043, 2024). "A less stringent suppression of UBA7 is also seen with MCF7 breast cancer cells, which also express high levels of USP18." (PMID 37756534, 2023). "We generated human leukemia THP-1 and breast cancer MDA-MB-231 USP18+/− (He) and USP18−/− (KO) cells and observed higher IFN signaling, DNA-damage response, and annexin V+ cells upon IFN treatment." (PMID 36646704, 2023). "Silencing USP18 inhibits the growth of mammary tumours in vivo and promotes the apoptosis of breast cancer cells." (PMID 32770981, 2020). "In Usp18 null mice, the growth of mammary tumor, angiogenesis and invasiveness of mammary epithelial tumor cells were reduced." (PMID 29416786, 2018). "Thus, in contrast to KCTD10, USP18 promotes the survival of breast cancer cells by stabilizing SLC7A11 to suppress ferroptosis." (PMID 38959043, 2024). "We next investigated whether USP18 also affected the cell viability of breast cancer cells via modulating ferroptosis." (PMID 38959043, 2024). "Breast cancer patients with high expression of both USP18 and Skp2 had the worst survival rates, which suggested that USP18/Skp2 may act as a potential biomarker in breast cancer." (PMID 34068643, 2021). "Additionally, USP18 depletion in the breast cancer cell line resulted in an increase in chemotherapy and IFNα-induced apoptosis with robust activation of caspase-8 and caspase-3." (PMID 32957626, 2020). "Furthermore, USP18 promotes breast cancer growth by enhancing the activity of the AKT/Skp2 pathway." (PMID 32770981, 2020). "In breast cancer, decreased cystine levels in the tumor microenvironment remodel the expression of KCTD10 and USP18, regulating SLC7A11 stability and subsequently cystine metabolism." (PMID 41330917, 2025). "Consistently, the high levels of SLC7A11 and USP18, and low levels of KCTD10 are coordinately coupled with decreased cystine levels in breast cancer tissues, indicating the pathological relevance." (PMID 38959043, 2024). "The IHC staining of human breast cancer tissues showed that in general, the SLC7A11 levels were positively correlated with USP18 levels, but negatively correlated with the KCTD10 levels in both nontumor and tumor tissues." (PMID 38959043, 2024). "Biologically, USP18 knockdown suppresses, whereas KCTD10 knockdown promotes growth of breast cancer cells via reducing or increasing SLC7A11, respectively." (PMID 40440083, 2024). "In clinical breast cancer samples, we found elevated levels of SLC7A11 and USP18, and reduced levels of KCTD10." (PMID 40440083, 2024). "Compared to normal tissues, expression of SLC7A11 and USP18 was increased, whereas expression of KCTD10 was decreased in multiple types of human cancers, including breast cancer." (PMID 38959043, 2024). "In human breast tumor tissues, mRNA levels of EIF2Ak2, USP18, DDX58, RBL2, STAT2, PGR, S1000A9, and CCND1 were significantly higher in ER+- than in ER--breast cancer tissues." (PMID 29416786, 2018). "From two pairs of matched breast cancer samples, we found that some of the detected CNVs contained some genes that were related to breast cancer, such as PDZK1, XRCC4, Fbxl17, ITGBL1, RORA, BAGE, AMOTL1, RAP80, PIWIL4, CSE1L, and USP18." (PMID 34262604, 2021).
breast carcinoma (continued). "The ultimate outcome of its anti-breast cancer effects may be dependent on the balance between IFN α/β signaling pathway and USP18-mediated cascade." (PMID 29416786, 2018). "Finally, we performed biological assays to determine whether KCTD10 or USP18 coordinates with SLC7A11 to regulate the cell viability and clonogenic survival of breast cancer cells." (PMID 38959043, 2024). "In breast cancer tissues with reduced cystine abundance, a negative correlation between KCTD10 and SLC7A11 and a positive correlation between USP18 and SLC7A11 were observed, respectively." (PMID 38959043, 2024).
COVID-19 (12 papers, 2021 to 2025). A disease caused by infection with severe acute respiratory syndrome coronavirus 2. "The KEGG pathways demonstrated that USP18 was related to antigen processing and presentation, COVID-19, and NOD-like receptor signaling pathway." (PMID 36582601, 2022). "However, Innate immune signatures such as MX1, USP18, and ISG15 in the NP were associated with Ct value at admission of COVID-19 patients." (PMID 39172244, 2024). "For example, IFI44L and USP18 are commonly up-regulated in both DS and COVID-19." (PMID 37379383, 2023). "We also identified genes that had not previously linked to COVID-19, such as USP18, an IFN-induced gene encoding a negative regulator of type I IFN signaling, which highly activated in unvaccinated Omicron patients and Alpha patients." (PMID 35784346, 2022). "Important gene combinations in the white blood cells of patients with COVID-19, including IFIT3, OASL, USP18, XAF1, IFI27, and EPSTI1, can be used for its diagnosis." (PMID 35928229, 2022). "Genes activated in the ‘no prior infection’ cohort, such as CCL2 and USP18, are part of the interferon response in severe COVID-19." (PMID 35441161, 2022).
melanoma (12 papers, 2014 to 2025). A malignant, usually aggressive tumor composed of atypical, neoplastic melanocytes. "It has been reported that USP18 enhances the resistance of BRAF-mutated melanoma cells to vemurafenib by stabilising cGAS expression and inducing autophagy." (PMID 40374599, 2025). "For example, USP18 enhances melanoma cell resistance to vemurafenib by stabilising cGAS expression, thereby inducing autophagy." (PMID 40374599, 2025). "Reports have shown that USP18 is involved in chronic myeloid leukaemia and melanoma by regulating IFN-modulating signaling, indicating its role in cancer-associated immune responses." (PMID 34001679, 2021). "Intriguingly, USP18 in B16 melanoma cells has been shown to attenuate tumor cell-mediated inhibition of T cell proliferation and suppress the expression of programmed cell death protein 1 (PD-1)." (PMID 32957626, 2020). "USP18 expression in B16 melanoma tumor cells also enhanced CTL activity during adoptive immunotherapy by prolonging the persistence and enhancing the activity of adoptively transferred CTLs and by reducing CTL exhaustion in the tumor microenvironment." (PMID 24884733, 2014). "In this report, we investigated the function of USP18 in IFN-γ signaling in B16 melanoma cells in vitro and in vivo and found that IFN-γ or CTLs activated USP18 expression in tumor cells." (PMID 24884733, 2014). "Ectopic expression or downregulation of USP18 in B16 melanoma tumor cells inhibited or promoted tumorigenesis, respectively, in immunocompetent mice." (PMID 24884733, 2014). "IFN-γ suppresses melanoma tumor growth by inducing ubiquitin-specific peptidase 18 (USP18) and sensitizing tumor cells to immunosurveillance, which may be limited by tumor-associated macrophages (TAMs)." (PMID 40108693, 2025). "To test whether our findings can be translated to solid cancer models, we generated Usp18+/+, Usp18+/−, and Usp18−/− B16F10 melanoma and MC38 colon cancer cells, subcutaneously injected them into mice, and monitored tumor growth." (PMID 36646704, 2023). "A previous study showed that USP18 is induced by IFN-β in HO-1 human melanoma cells." (PMID 26240016, 2015). "This study is not only important for elucidating the regulation of CTL immunotherapy, but also provides a scientific basis for developing novel immunotherapeutic strategies to target USP18 in B16 melanoma cells to induce innate and adaptive immune responses against tumors." (PMID 24884733, 2014). "In this study, USP18 in tumorigenesis and anti-tumor immune response was comprehensively appraised in vivo by overexpression or downregulation its expression in murine B16 melanoma tumor model in immunocompetent and immunodeficient mice." (PMID 24884733, 2014). "Next, we investigated the possibility that use of USP18 could enhance CTL activity against subcutaneous B16 melanoma." (PMID 24884733, 2014). "USP18 expression in B16 melanoma tumor cells regulated IFN-γ-mediated immunoediting, including upregulating MHC class-I expression, reducing tumor cell-mediated inhibition of T cell proliferation and activation, and suppressing PD-1 expression in CD4+ and CD8+ T cells in tumor-bearing mice." (PMID 24884733, 2014). "Alternatively, USP18 antagonists or strategies promoting USP18 degradation could promote the beneficial effect of therapeutic IFNs used in multiple sclerosis, hairy cell leukemia, and melanoma." (PMID 32039148, 2019). "Furthermore, ubiquitin-specific peptidase 18 (USP18), a negative regulator of type I IFN signaling, appeared to be critical for differentiation of tumor-supportive TAMs in B16F10 melanomas." (PMID 40098954, 2025). "Accordingly, myeloid-specific deletion of USP18, a negative regulator of type I IFN signaling, resulted in both increased infiltration of CD8+ T cells, especially central memory cells, into B16F10 melanomas and enhanced expression of activation markers (CD69, IFN-γ, perforin) in these T cells." (PMID 40098954, 2025).
melanoma (continued). "USP18 was first discovered during the analysis of differentially expressed genes in AML1-ETO knock-in mice and later in virus-infected porcine alveolar macrophages and human melanoma cell lines." (PMID 32957626, 2020).